WIF1 (Wnt inhibitory factor 1)
Diseases named in the same sentence as WIF1 in open-access papers (continued):
Sharing a sentence is not in itself a finding about the gene and the disease.
leiomyoma (1 paper, 2023). A well-circumscribed benign smooth muscle neoplasm characterized by the presence of spindle cells with cigar-shaped nuclei, interlacing fascicles, and a whorled pattern. "This analysis indicated that the expression of WNT16, CACNA1D, DCX, and WIF1 was significantly higher, while the expression of MTMR8 was significantly lower in myometrium adjacent to MED12-mutated leiomyomas compared to myometrium adjacent to MED12 wild-type leiomyomas." (PMID 36835153, 2023). "An unexpected finding was the overexpression of the WNT inhibitory factor (WIF1) in leiomyomas." (PMID 36835153, 2023). "Others have also reported overexpression of WIF1 and other WNT-protein inhibitors such as SFRP1, FBXW11, NKD1, and SFPR4 in leiomyomas." (PMID 36835153, 2023).
leukopenia (1 paper, 2022). "The rs3782499 in WIF-1 gene was related to fever, leukopenia, and the rs1569198 in DKK-1 was linked to sputum smear-positive in PTB patients." (PMID 36569862, 2022). "For WIF-1 gene rs3782499, PTB patients carrying the homozygous TT/CC genotype had a highly significant association with increased frequency of fever, and carrying the C allele had a lower frequency of leukopenia (P = 0.032, P = 0.048, respectively)." (PMID 36569862, 2022).
lymph node metastasis (1 paper, 2016). "Furthermore, though no statistical significance was registered, the expression of WIF1 was much lower in the patients with surgical margin involvement (14.3%) and lymph node metastasis (14.8%) than in those with no surgical margin involvement (24.3%) or no lymph node metastasis (27.5%)." (PMID 27843945, 2016).
metastatic disease (1 paper, 2010). "Blocking Wnt signaling in PCa by WIF1 may represent a novel strategy in the future to reduce metastatic disease burden in PCa patients." (PMID 20573255, 2010). "Although WIF1 has been shown to act as a tumor suppressor, inhibiting cancer cell proliferation in many cancers, little is known about its potential effect on metastatic tumors and the process of tumor metastasis." (PMID 20573255, 2010).
neurodegenerative eye diseases (1 paper, 2024). "Further, the regulation of Wnt-inhibitory factor 1 (WIF1), a secreted Wnt signaling antagonist, has not been fully characterized in neurodegenerative eye diseases." (PMID 38448948, 2024).
oral squamous cell carcinoma (1 paper, 2015). "The methylation of DACH1, DKK1, LKB1, PPP2R2B, RUNX3, SFRP2, and WIF-1 was analyzed in 16 oral squamous cell carcinoma cell lines using the methylation-specific polymerase chain reaction." (PMID 25487617, 2015). "Based on these results, we identified DACH1, DKK1, and WIF-1 as potential epimarkers in OSCC and further analyzed their methylation in a group of oral squamous cell carcinoma patients." (PMID 25487617, 2015). "In the first stage, 16 oral squamous cell carcinoma cell lines were screened for the methylation of DACH1, DKK1, LKB1, PPP2R2B, RUNX3, SFRP2, and WIF-1 using methylation-specific PCR." (PMID 25487617, 2015).
oropharyngeal cancer (1 paper, 2015). Carcinoma, predominantly squamous cell, arising from the epithelial cells of the oropharynx. "In this regard, frequent hypermethylation of the negative regulators of this pathway (DKK-3, RUNX3, SFRP1, SFRP2, SFRP4, SFRP5, and WIF1) was observed in oral and oropharyngeal cancers." (PMID 25487617, 2015).
oropharyngeal squamous cell carcinoma (1 paper, 2015). "In summary, our current study showed that DACH1, DKK1, and WIF-1 are methylated in oral and oropharyngeal squamous cell carcinomas." (PMID 25487617, 2015).
oropharyngeal tumors (1 paper, 2017). "It is noteworthy that the WIF-1 gene methylation is correlated with shorter survival for oropharyngeal tumor patients." (PMID 28708091, 2017). "Similarly, the WIF-1 gene is frequently methylated in patients with primary oropharyngeal tumors." (PMID 28708091, 2017).
parathyroid tumors (1 paper, 2016). "We have examined the methylation status of the secreted Wnt antagonists (sFRP, DKKs and WIF1) and observed no methylation changes in MEN1-parathyroid tumors compared to normal parathyroid tissues." (PMID 26871472, 2016).
pemphigus (1 paper, 2021). Pemphigus is a group of rare autoimmune diseases that cause blistering of the skin and mucous membranes (mouth, nose, throat, eyes, and genitals).This conditioncan occur at any age, but often strikes people in middle or older age. "Several other skin homeostatic genes, including WIF1, EDA, RXRG, and TGFB2, were significantly decreased in pemphigus cases." (PMID 34660634, 2021). "Direct comparison of our dataset to previously published human pemphigus datasets revealed five conserved differentially expressed genes: CD19, WIF1, CXCL10, CD86, and S100A12." (PMID 34660634, 2021).
periodontitis (1 paper, 2022). An acute or chronic inflammatory process that affects the tissues that surround and support the teeth. "JUN, FOS, KLF2, THBS1 and WIF1 were identified as key regulator in periodontitis and validated to be highly expressed in IPT through RT-qPCR." (PMID 36045361, 2022). "Five mRNAs, i,e., FOS, JUN, KLF2, WIF1, and THBS1, for further validation via RT-qPCR on 15 periodontitis and 15 healthy gingivae samples." (PMID 36045361, 2022).
pituitary adenomas (1 paper, 2019). "Secreted frizzled-related protein 1(sFRP1) and Wnt inhibitory factor 1(WIF-1) genes were found to be less expressed in invasive non-functioning pituitary adenomas." (PMID 30733705, 2019).
polyp (1 paper, 2008). A usually exophytic mass attached to the underlying tissue by a broad base or a thin stalk. "Similarly, CGI methylation of SFRP4, SFRP5 and WIF1 correctly identified 61.5% of polyp patients and 78.9% of neoplasia-free subjects (P=0.0167)." (PMID 18542073, 2008).
preeclampsia (1 paper, 2022). Preeclampsia is a hypertensive disorder of pregnancy that is characterized by new-onset hypertension with proteinuria presenting after 20 weeks of gestation, and depending on mild or severe forms may initially present with severe headache, visual disturbances, and hyperreflexia. "WIF1 is involved in the regulation of reproductive performance by the Wnt signalling pathway, and WIF1 overexpression may be related to the pathogenesis of preeclampsia." (PMID 36139290, 2022).
renal carcinoma (1 paper, 2012). A carcinoma arising from the epithelium of the renal parenchyma or the renal pelvis. "The methylation levels of six Wnt antagonist genes (sFRP-1, sFRP-2, sFRP-4, sFRP-5, Wif-1, and Dkk-3) were significantly higher in renal cancer compared to normal renal tissues." (PMID 22325146, 2012). "CpG promoter hypermethylation has been often found in antagonists of the Wnt pathway, the SFRP family, WNT inhibitory factor-1 and DICKKOPF family members after comparing primary renal cancer samples to the corresponding normal renal tissues." (PMID 22325146, 2012). "The Wnt inhibitory factor-1 (WIF-1) promoter was found to be hypermethylated in RCC and its over-expression inhibited Wnt activity and induces apoptosis in renal cancer cells." (PMID 22325146, 2012).
renal fibrosis (1 paper, 2022). A final common manifestation of a wide variety of chronic kidney diseases characterized by glomerulosclerosis and tubulointerstitial fibrosis. "Here we found that blockade of WIF1 secretion by genetic deletion of Cldn5 or Wif1 in podocytes markedly enhanced renal fibrosis after UUO." (PMID 35332151, 2022). "Systemic delivery of WIF1 could attenuate DN and UUO-induced renal fibrosis, introducing WIF1 as a therapeutic target for mitigating kidney injury." (PMID 35332151, 2022).
salivary gland carcinoma (1 paper, 2016). A carcinoma that arises from the major or minor salivary glands. "Lately, a downregulation of the Wnt inhibitory factor 1 (WIF1) as a widespread event in salivary gland carcinoma ex-pleomorphic adenoma (CaExPA), has been described." (PMID 27766946, 2016).
sarcoidosis (1 paper, 2025). Sarcoidosis is a multisystemic disorder of unknown cause characterized by the formation of immune granulomas in involved organs. "Among the twelve common DEGs, SALL4, WNT10A, RASAL1, CAMK2B were significantly upregulated while GADD45B, KLF4, OLR1, CSF3, WIF1, RAMP3 and AGER downregulated in both sarcoidosis and LC as compared to the controls." (PMID 40797277, 2025).
schistosomiasis (1 paper, 2016). An infectious disease caused by parasitic trematodes of the genus Schistosoma that colonize human blood vessels and release eggs that can cause granulomatous reactions leading to acute (swimmer's itch or acute schistosomiasis syndrome) or chronic disease. "In another type of urinary tract infection, schistosomiasis, DNA methylation of WIF1 was found in human and mouse samples." (PMID 26964089, 2016).
schizophrenia (1 paper, 2022). A major psychotic disorder characterized by abnormalities in the perception or expression of reality. "Our findings reveal the pathogenetic role of OPC-specific DISC1-Δ3 variant in the onset of schizophrenia and highlight the therapeutic potential of Wif1 as an alternative target for the treatment of this disease." (PMID 36131044, 2022). "Mechanistically, we demonstrated that mice with enhanced DISC1-Δ3 variant expression in OPCs display schizophrenia-like behaviors and synaptic defects, both driven by the overactivated Wnt/β-catenin-Wnt inhibitory factor 1 (Wif1) cascade." (PMID 36131044, 2022). "In conclusion, our findings provide new evidence of the pathological potential of OPCs in the onset of schizophrenia in genetically susceptible individuals, whereas targeting Wif1 in OPCs may open a new direction in developing effective therapeutic strategies for schizophrenia." (PMID 36131044, 2022). "Our results provide an alternative insight into the critical role of malfunctional OPCs in pathogenesis of schizophrenia and highlight a molecular target, Wif1, for developing potential therapeutic strategies." (PMID 36131044, 2022). "Taken together, our results from the DISC1-Δ3 mouse model indicate that Wnt-hyperactivation in the OPCs can disrupt synapse formation and initiate the pathogenesis of schizophrenia by overproduction of Wnt inhibitor Wif1." (PMID 36131044, 2022). "Notably, manipulating Wif1 production alone improves synaptogenesis and mitigates schizophrenia-like behaviors in DISC-Δ3 mice." (PMID 36131044, 2022). "This new mechanism is in agreement with observations showing altered Wnt pathway genes such as GSK3β, WIF1, as well as AKT1 in schizophrenia postmortem brains." (PMID 36131044, 2022).
scrub typhus (1 paper, 2021). Scrub typhus is a rare dust mite-borne infectious disease caused by the Orientia tsutsugamushi bacterium and characterized clinically by an eruptive fever which is potentially serious. "Levels of SOST and in particular sFRP-3 and WIF-1 were markedly increased in scrub typhus patients at admission to the hospital compared to healthy controls and notably for sFRP-3 and WIF-1, also when compared to admission levels in infectious controls." (PMID 33914733, 2021). "We hypothesized that plasma levels of the secreted Wnt modulators sFRP-3, DKK-1, SOST and WIF-1 would be regulated in scrub typhus and correlate with markers of inflammation and immune activation." (PMID 33914733, 2021). "We found i) Levels of SOST and in particular sFRP-3 and WIF-1 were markedly increased and DKK-1 decreased in scrub typhus patients at admission to the hospital compared to healthy controls." (PMID 33914733, 2021).
squamous cell carcinoma (1 paper, 2017). A carcinoma arising from squamous epithelial cells. "WIF-1 hypermethylation is predominant in squamous cell carcinoma (SCC), suggesting that WIF-1 methylation contributes to the development of NSCLC, especially SCC." (PMID 27911280, 2017).
synucleinopathies (1 paper, 2023). "However, this more detailed analysis revealed that Wnt inhibitory factor 1 (WIF-1) can distinguish tauopathies from PD and synucleinopathies." (PMID 37667404, 2023).
thyroid tumor (1 paper, 2025). A benign or malignant neoplasm affecting the thyroid gland. "We found new characteristics of thyroid tumors, such as methylation of TP73, WIF1, and PDLIM4 TSGs, which can contribute to thyroid neoplasia." (PMID 41150811, 2025).
Ureteral obstruction (1 paper, 2022). Obstruction of the flow of urine through the ureter. "Podocyte-derived WIF1 also plays paracrine roles in tubular epithelial cells, as evidenced by the finding that animals with podocyte-specific deletion of Cldn5 or Wif1 have worse kidney fibrosis after unilateral ureteral obstruction than littermate controls." (PMID 35332151, 2022).
urinary tract infection (1 paper, 2016). "Interestingly, epigenetic repression of WIF1 also occurs during urinary tract infection induced by schistosomes." (PMID 26964089, 2016).
urothelial carcinoma (1 paper, 2014). A malignant neoplasm derived from the transitional epithelium of the urinary tract (urinary bladder, ureter, urethra, or renal pelvis). "Wif1 is frequently hypermethylated in urothelial carcinoma and its knockdown increases the cell proliferation rate, probably through increased transcription of c-Myc." (PMID 24816560, 2014).
valvular heart disease (1 paper, 2022). "In this study, we present baseline plasma concentrations of WNT-5a, sFRP-1, sFRP-5, and WIF-1 in patients with coronary and/or valvular heart disease." (PMID 36440011, 2022).
vitiligo (1 paper, 2020). Generalized well circumscribed patches of leukoderma that are generally distributed over symmetric body locations and is due to autoimmune destruction of melanocytes. "WIF1 promotes melanogenesis in normal human melanocytes, though it is not yet clear what impact a loss of expression would have on vitiligo or VKH." (PMID 33384688, 2020). "IGFBP5, FOXO1, and WIF1 downregulation may indicate a loss of tolerance mechanisms or melanocyte regenerative capacity in the skin in canine VKH and vitiligo." (PMID 33384688, 2020).
tumor (155 papers, 2006 to 2025). "WIF1 is a tumor suppressor that encodes for a secreted antagonist that binds Wnt proteins hampering ligand–receptor interactions." (PMID 32550265, 2020). "It is also predicted to result in the loss of the WIF domain of WIF1, required for its tumor suppressor activities, with ensuing Wnt signaling activation." (PMID 32550265, 2020). "WIF1 encodes for a tumor suppressor that modulates Wnt signaling, a role that requires an intact WIF domain." (PMID 30675516, 2019). "The WIF-1 methylation was associated with the tumor, node, and metastasis (TNM) (P = 0.003) and the age (P = 0.014)." (PMID 29147412, 2015). "Methylation of SFRP4, WIF1 and WNT5a genes were meaningfully associated with increasing tumor stage (p = 0.004, p = 0.029 and p = 0.004)." (PMID 25107489, 2014). "In a similar model with the results of the urine or serum Wif-1 methylation test (model 2), a positive Wif-1 methylation test was strongly associated with advanced neoplasia (lower bound of 95% CI: 18.7)." (PMID 25025467, 2014). "We found that methylated Wif-1 had the highest diagnostic performance to predict advanced neoplasia compared to clinical characteristics, FOBTs and microbiota changes, alone or in combination." (PMID 25025467, 2014). "High expression of WIF1 was significantly associated with big tumor diameters and deep invasion, while loss of SFRP1 expression was significantly associated with the left lesion site, deep invasion, and high TNM stage." (PMID 24949429, 2014). "Wnt inhibitor factor 1 (WIF-1) is a tumor suppressor gene that mainly encodes secreted proteins." (PMID 33033505, 2020). "Thus, WIF1-promoter methylation assays confirmed the presence of circulating tumor DNA in 60% of mCRC with disappearance of RAS mutations during treatment." (PMID 32766143, 2020). "Moreover, methylation frequency of SFRP4 and WIF1 genes were also significantly associated with tumor differentiation (p = 0.009 and p = 0.031)." (PMID 25107489, 2014). "Loss of WIF1 expression leads to aberrantly activate Wnt signaling, which is associated with cancer and could act as a tumor suppressor gene." (PMID 24289328, 2013). "Along this line, WIF-1 methylation may serve as a diagnostic tumor biomarker." (PMID 34488905, 2021). "Thus, genetic alterations of β-catenin and epigenetics-related Wif-1 promoter hypermethylation may be important mechanisms underlying AC tumor formation though aberrant canonical Wnt/β-catenin signaling activation." (PMID 24755523, 2014). "Conversely, WIF1 acts as an antagonist of the Wnt signaling pathway, and its reduced expression in GBM is linked to shorter survival, suggesting a tumor suppressor role." (PMID 41179304, 2025). "miR-181a has strong tumor-promoting effects by inhibiting the expression of WIF-1 and has a potential role in inducing epithelial–mesenchymal transition." (PMID 40693022, 2025). "WIF1 suppresses tumor vessel growth and induces cancer cell apoptosis by reducing the expression of proteins, such as c-myc, cyclinD1, stromal-derived factor-1α (SDF-1α), and VEGF." (PMID 38448948, 2024). "In particular, the expression of WNT inhibitory factor 1 (Wif1), a canonical tumor suppressor, and insulin receptor substrate 2 (Irs2), were decreased with age in both Glut4m and WT mice." (PMID 38161415, 2024). "On the contrary, inhibiting the expression of has-miR-181a and increasing the expression of WIF-1 can inhibit tumor growth and metastasis." (PMID 38584703, 2024). "The study found that has-miR-181a promotes cell proliferation and invasion by combining with the tumor suppressor WIF-1." (PMID 38584703, 2024). "The methylation levels of SFRP1, SFRP2, and Wnt inhibitory factor-1 (WIF1) in tumor tissues were found to be significantly upregulated compared to adjacent non-neoplastic tissues." (PMID 38464391, 2024).